VMP1 (vacuole membrane protein 1)
Diseases named in the same sentence as VMP1 in open-access papers (continued):
Sharing a sentence is not in itself a finding about the gene and the disease.
glioma (continued). "Data from TCGA and GTEx databases revealed that VMP1 was overexpressed in the lower grade glioma (LGG; n = 518) and GBM sample (n = 163) compared with the normal brain tissue (n = 207)." (PMID 34311746, 2021). "Mechanistically, VMP1 knockout blocked autophagic flux and thus sensitized glioma cells to radiotherapy and chemotherapy." (PMID 34311746, 2021). "In multivariate analysis, high VMP1 expression was independently related with a poorer OS in glioma (HR = 1.12, 95% CI 1.02–1.24, P = 0.01)." (PMID 34311746, 2021). "Consistent with results obtained for ovarian cancer and acute myeloid leukemia, our study of glioma revealed that VMP1 overexpression is related to disease progression and a poor prognosis, and VMP1 KO inhibits cell proliferation and induces cell death." (PMID 34311746, 2021). "In this study, we clearly establish the prognostic value of VMP1 in glioma based on bioinformatics and cell-based analyses." (PMID 34311746, 2021). "The expression of VMP1 and clinicopathologic data for 1996 glioma samples were collected from authoritative public databases to explore its prognostic value." (PMID 34311746, 2021). "We demonstrate that VMP1 is overexpressed in gliomas and could confer survival advantages through enhanced angiogenesis, and that bevacizumab (BEV), a VEGFA‐targeted therapy, effectively suppresses VMP1‐driven tumor growth." (PMID 41589276, 2026). "VMP1 has the potential to be utilized as a predictor of survival for glioma patients." (PMID 39273093, 2024). "Moreover, they observed a gradual increase in VMP1 expression from glioma grade 2 to grade 4, confirming these results by applying immunohistochemistry to human glioma specimens." (PMID 38612567, 2024). "They found that VMP1 is overexpressed in glioma and glioblastoma." (PMID 38612567, 2024). "Further validation on reverse experiment and in vivo studies could contribute to confirm the relevance of VMP1 in glioma growth." (PMID 34311746, 2021). "Herein, we systematically evaluated VMP1 expression in different grade of glioma." (PMID 34311746, 2021). "Moreover, a nomogram model showed that VMP1 expression has high prognostic value for determining survival in glioma." (PMID 34311746, 2021). "In our research, VMP1 KO disrupted autophagosome formation and fusion with lysosomes, which reduced catabolites for recycling and inhibited energy metabolism, thus sensitizing glioma cells to radiotherapy and chemotherapy." (PMID 34311746, 2021). "Together, these findings indicate that VMP1 may act as an oncogene that promotes glioma progression." (PMID 34311746, 2021). "Our results provide evidence for the prognostic value of VMP1 in glioma." (PMID 34311746, 2021). "We hypothesized that VMP1 contributes to glioma progression by modulating autophagy." (PMID 34311746, 2021). "To further validate the functions of VMP1, we used the CRISPR-Cas9 gene editing system for VMP1 depletion in the glioma cell line LN299." (PMID 34311746, 2021). "However, the contribution of VMP1 to glioma development as well as its prognostic value has not been established." (PMID 34311746, 2021).
inflammatory bowel disease (6 papers, 2019 to 2026). A spectrum of small and large bowel inflammatory diseases of unknown etiology. "In recent years, this region of VMP1 has been consistently reported as hypomethylated in blood of patients with inflammatory bowel disease (IBD), Crohn’s disease (CD), and ulcerative colitis (UC)." (PMID 35177097, 2022). "Moreover, CpGs in the VMP1/MIR21 locus are also among the top hits in several previous EWAS, including chronic inflammation marker C-reactive protein (CRP), cardiovascular biomarker GDF-15, obesity, childhood-onset Crohn’s disease, and inflammatory bowel disease." (PMID 30867049, 2019).
lung carcinoma (5 papers, 2013 to 2025). "We further generated clonal TMEM41B KO and VMP1 KO cell lines using human lung carcinoma epithelial cells, A549 cells, to demonstrate that these phenotypes were not limited to only a specific cell type." (PMID 35939522, 2022). "miR-21 is located in 3'UTR of VMP1 (vacuole membrane protein 1) gene at chromosome 17q23.2, a region amplified in BC and also in neuroblastomas, colon and lung cancers." (PMID 26391647, 2015).
ovarian carcinoma (5 papers, 2021 to 2024). A malignant neoplasm originating from the surface ovarian epithelium. "This downregulation of VMP1 is associated with enhanced cell migration in ovarian cancer cell lines." (PMID 38612567, 2024). "These seemingly contradictory findings highlight the complex and multifaceted role of VMP1 in ovarian cancer progression." (PMID 38612567, 2024). "Two studies contribute valuable insights into the role of VMP1 in ovarian cancer; however, they present conflicting perspectives." (PMID 38612567, 2024). "Therefore, the role of VMP1 in ovarian cancer malignancy is likely related to the genetic context of each particular tumor, warranting further investigation to elucidate the underlying mechanisms and potential therapeutic implications." (PMID 38612567, 2024). "Additionally, the downregulation of VMP1 in this context correlates with reductions in cell proliferation and invasion in ovarian cancer cell lines." (PMID 38612567, 2024). "However, the opposite results have been observed in ovarian cancer and acute myeloid leukemia, in which elevated VMP1 expression contributes to cancer progression and is associated with a poor prognosis." (PMID 34311746, 2021). "In ovarian cancer, VHL inactivation promotes cell migration by stabilizing HIF-1α, upregulating miR-210, and diminishing VMP1 expression." (PMID 38612567, 2024).
breast tumor (4 papers, 2007 to 2026). "Further analyses were performed in the Nordic and TCGA cohorts to explore the potential role of VMP1 in breast tumor development." (PMID 31442252, 2019). "In breast tumors from cohort 1, higher VMP1 expression level was observed in ERBB2/HER2 positive tumors based on classification with immunohistochemistry (HER2, p = 7x10-4) or molecular subtyping (p = 5x10-6, )." (PMID 31442252, 2019). "Further studies are needed in cell based systems to elucidate the role of VMP1 in breast tumor development." (PMID 31442252, 2019). "VMP1 is located at 17q23, a chromosomal region whose copy number is increased in up to 22% of primary breast tumors depending on their histological origin." (PMID 31442252, 2019). "Herein, we describe a screen of fusion genes in a large group of breast tumors and in BC cell lines that identified vacuole membrane protein 1 (VMP1) as a gene that may contribute to breast tumor progression." (PMID 31442252, 2019). "Taken together, the data presented suggest that high VMP1 expression may be a marker of poor prognosis in BC, particularly in HER2 positive breast tumors." (PMID 31442252, 2019). "Summary figures for SE regions near VMP1/MIR21 (Chr 17), SUMO1P1 (Chr 20), and PVT1 (Chr 8) are shown as representative examples from cluster A, B, and D, respectively, showing higher accessibility in non-basal compared with basal breast tumor samples." (PMID 38625038, 2024).
glioblastoma (4 papers, 2013 to 2026). The most malignant astrocytic tumor (WHO grade IV). "In Glioblastoma, elevated expression of VMP1 was associated with an advanced disease stage, while CRISPR-Cas9-mediated VMP1 depletion inhibited cell proliferation and enhanced cell death." (PMID 37190091, 2023). "Our study thus uncovered non‐autophagic functions of VMP1 as an important mediator in glioblastoma angiogenesis with the potential for therapeutic targeting." (PMID 41589276, 2026). "Bulk, single‐cell, and spatial transcriptomics analyses revealed that the pro‐angiogenic markers were enriched in glioblastomas with high VMP1 expression." (PMID 41589276, 2026). "VMP1 promotes angiogenesis in glioblastoma (GBM) through VEGFA‐VEGFR2 signaling and activation of endothelial cells." (PMID 41589276, 2026). "We observed significant upregulation of VMP1 in glioblastoma, which was correlated with poorer prognosis, and its ability to promote tumor growth without altering autophagic flux." (PMID 41589276, 2026). "Here, using glioblastoma as a cancer model, we found that VMP1 can promote tumor growth independent of its autophagic functions." (PMID 41589276, 2026). "Aligning with this pro‐oncogenic role, VMP1 was found to be correlated with poor prognoses and overexpressed in both triple‐negative breast cancer and glioblastoma (GBM)." (PMID 41589276, 2026).
acute kidney injury (3 papers, 2022 to 2025). Sudden and sustained deterioration of the kidney function characterized by decreased glomerular filtration rate, increased serum creatinine or oliguria. "A study indicated a correlation between septic shock and acute kidney injury (AKI), revealing that the genes PTX3, VMP1, OLFM4, SLPI, TIMP1, LCN2, and S100A9 are strongly correlated with novel biomarkers implicated in the onset and progression of sepsis‐associated acute kidney injury (SSAKI)." (PMID 41394771, 2025). "Sepsis may also induce acute kidney injury (AKI), and studies showed that VMP1, SLPI, PTX3, TIMP1, OLFM4, LCN2, and S100A9 genes were markedly correlated with the development and progression of septic-shock-associated AKI." (PMID 36299685, 2022).
acute myeloid leukemia (3 papers, 2019 to 2023). Acute myeloid leukemia (AML) is a group of neoplasms arising from precursor cells committed to the myeloid cell-line differentiation. "In the present study the role of VMP1 was analysed in CD34+ cells of cord blood (CB) and primary acute myeloid leukemia (AML) cells and cell lines." (PMID 31142733, 2019).
esophageal cancer (3 papers, 2019 to 2025). A primary or metastatic malignant neoplasm involving the esophagus. "While VMP1 expression appears to be directly associated with a pro-malignant role in both gastric and esophageal cancer, it is crucial to highlight that, in esophageal cancer, the elevated expression involves an abnormal protein that comprises only the C-terminal of VMP1." (PMID 38612567, 2024). "In the context of human samples of esophageal cancer analyzed through RNA sequencing, polymerase chain reaction (PCR), and Sanger sequencing techniques, a notable finding involves the fusion of VMP1 with Ribosomal Protein S6 Kinase B1 (RPS6KB1)." (PMID 38612567, 2024). "RPS6KB1::VMP1 (NSCLC P13041) translocation is a recurrent event in esophageal cancer." (PMID 40661875, 2025).
metabolic dysfunction-associated steatohepatitis (3 papers, 2024 to 2026). Metabolic dysfunction-associated steatohepatitis (MASH, formerly known as nonalcoholic steatohepatitis or NASH) is a type of fatty liver disease. "Mice with liver deficiency VMP1 also had impaired VLDL secretion and developed nonalcoholic steatohepatitis NASH." (PMID 40723862, 2025). "VMP1 deficiency in mice recapitulates key features of non-alcoholic steatohepatitis, while VMP1 overexpression mitigates steatosis in non-alcoholic steatohepatitis, underscoring its essential role in the pathogenesis of non-alcoholic fatty liver disease." (PMID 39100095, 2024). "Loss of hepatic TMEM41B or VMP1 results in severe defects in VLDL secretion and leads to the rapid development of metabolic dysfunction-associated steatohepatitis (MASH) in mice." (PMID 41539605, 2026).
viral infections (3 papers, 2022 to 2025). "Recent research has also implicated VMP1 in cellular defense mechanisms against viral infections and in lipid droplet (LD) metabolism." (PMID 40629421, 2025). "Recent studies have also linked VMP1 to the cellular response against viral infections and lipid droplet (LD)." (PMID 39100095, 2024). "Upon the cDNA complementation, DENV infection was rescued to levels comparable to the WT cells, reinforcing that both TMEM41B and VMP1 deficiencies are indeed responsible for the observed diminished levels of viral infections." (PMID 35939522, 2022). "VMP1’s functions extend beyond autophagy, with emerging evidence highlighting its significance in modulating ER calcium levels, which are paramount for protein folding, cellular signaling, and responses to viral infections." (PMID 39100095, 2024). "Given the integral function of VMP1 in preserving ER calcium homeostasis and the ER’s pivotal role in the replication of viruses, it is plausible that VMP1 may exert regulatory control over viral infection via the modulation of ER calcium ions." (PMID 39100095, 2024). "VMP1 has roles that go beyond its involvement in autophagy, with growing evidence indicating its importance in regulating endoplasmic reticulum calcium homeostasis—an essential factor for proper protein folding, intracellular signaling, and cellular responses to viral infection." (PMID 40629421, 2025). "Intriguingly, the FA treatment could not rescue HCoV-OC43 infection in both TMEM41B- and VMP1-deficient cells, hinting that deprived cellular FAs in these clonal KO cells might not solely be responsible for diminished viral infection." (PMID 35939522, 2022). "Further studies are needed to elucidate the molecular mechanisms by which VMP1 and TMEM41B are recruited in viral infections and how these ER membrane proteins distinctively impact different families of enveloped viruses." (PMID 35939522, 2022). "Surprisingly, MDA5 and RIG-I deficiencies (RIG-I and MDA5 double-KO) did not promote DENV replication in any of the conditions, indicating that the upregulation of the dsRNA sensors is unlikely to be the main contributing factor to the diminished viral infection in TMEM41B KO and VMP1 KO cells." (PMID 35939522, 2022). "Whether VMP1 and TMEM41B cooperate in augmenting viral infections has yet to be elucidated." (PMID 35939522, 2022).
bladder cancer (2 papers, 2013 to 2025). "To investigate the protein expression profiles of six genes (ABCA7, HOOK2, JUNB, RHOB, VMP1, and ACTG1) that significantly impact both DSS and PFI in bladder cancer patients, we conducted Western blot analyses using SV-HUC-1 and 5637 cell lines." (PMID 40574864, 2025).
diabetes (2 papers, 2020 to 2022). "streptozotocin (STZ)-induced diabetes leads to activation of VMP1-mediated autophagy in pancreatic β cells after 3 h administration." (PMID 33041786, 2020). "The early detection of VMP1 and autophagic signals in STZ-treated rats and cells indicates that increased autophagy expression and related signals in β cells may play an important role as the recognized biomarkers of diabetes development." (PMID 33041786, 2020).
Flavivirus Infections (2 papers, 2022 to 2024). Infections with viruses of the genus FLAVIVIRUS, family FLAVIVIRIDAE. "Where upon flavivirus infection and translation of the viral polyprotein, TMEM41B is recruited to sites on the ER membrane together with NS4A and NS4B where replication complexes are forming, and interacts with the VMP1 protein to form DMV." (PMID 39100095, 2024). "Cells lacking VMP1 were significantly resistant to flavivirus infection and somewhat resistant to coronavirus infection; however, in-depth mechanistic studies on how VMP1 interferes with virus replication were not performed." (PMID 35245334, 2022). "Additionally, VMP1 and TMEM18 also play significant roles in flavivirus infection." (PMID 39100095, 2024).
gastric cancer (2 papers, 2023 to 2024). A primary or metastatic malignant neoplasm involving the stomach. "Consistently, by analyzing human datasets, VMP1 has been identified as a hub gene that is differentially expressed in gastric cancer." (PMID 38612567, 2024).
kidney cancer (2 papers, 2012 to 2023). Primary or metastatic malignant neoplasm involving the kidney. "Finally, our cellular experiments displayed that the proliferation and migration of kidney cancer cells were reduced and apoptosis levels were increased after vacuole membrane protein 1 (VMP1) knockdown, revealing that it may be a key oncogene and a possible breakthrough point for treatment." (PMID 37035172, 2023).
leukemia (2 papers, 2013 to 2023). A malignant (clonal) hematologic disorder, involving hematopoietic stem cells and characterized by the presence of primitive or atypical myeloid or lymphoid cells in the bone marrow and the blood. "VMP1 (vacuole membrane protein-1) overexpression increased autophagic flux and improved mitochondrial quality, which coincided with an increased threshold for venetoclax-induced loss of mitochondrial outer membrane permeabilization (MOMP) and apoptosis in leukemia cells." (PMID 37296673, 2023).
liver cancer (2 papers, 2020 to 2021). An epithelial or non-epithelial malignant neoplasm that arises from the liver. "VMP1 was initially reported to regulate tumor cell migration and invasion in a liver cancer study." (PMID 34631221, 2021).
pancreatic ductal adenocarcinoma (2 papers, 2019 to 2020). An infiltrating adenocarcinoma that arises from the epithelial cells of the pancreas. "In pancreatic cells, VMP1-induces autophagy and the KRASG12D mutation co-operates to promote the formation of pancreatic ductal adenocarcinoma." (PMID 31442252, 2019).
Parkinson disease (2 papers, 2022 to 2023). A progressive degenerative disorder of the central nervous system characterized by loss of dopamine producing neurons in the substantia nigra and the presence of Lewy bodies in the substantia nigra and locus coeruleus. "Altered expression of vacuole membrane protein 1 (VMP1) has recently been observed in the context of multiple sclerosis and Parkinson's disease (PD)." (PMID 36747822, 2023). "Following that, we analyzed the alteration in the VMP1 expression of PD with the disease duration, M-HY score, and anti-Parkinson drug use status." (PMID 35464320, 2022).
steatosis (2 papers, 2015 to 2024). Increased lipid within the cytoplasm of cells. "In addition to the GA-II example of IEM, we show here that the vmp1 mutation causes steatosis (7466mu110 mutant); there is no animal model of this mutation reported." (PMID 25950913, 2015).
Arrhythmia (1 paper, 2026). Any cardiac rhythm other than the normal sinus rhythm. "VMP1 expression is up-regulated in cardiomyocytes after birth, and its genetic deletion causes severe arrhythmias, dilated cardiomyopathy, and sudden cardiac death." (PMID 42284404, 2026).
asthma (1 paper, 2025). "Among these genes, VMP1, ZNF205, ZNF205, and LGALS3BP showed significant reductions (p < 0.05) in expression between the healthy and asthma groups." (PMID 39858200, 2025).
chorea-acanthocytosis (1 paper, 2021). Chorea-acanthocytosis (ChAc) is a form of neuroacanthocytosis and is characterized clinically by a Huntington disease-like phenotype with progressive neurological symptoms including movement disorders, psychiatric manifestations and cognitive disturbances. "Research in Dictyostelium has demonstrated a link between the neurodegenerative disease, Chorea-acanthocytosis (ChAc), and autophagy, with further research implicating Vmp1, an ER protein involved in cancer, in the clearance of ubiquitinated protein aggregates through autophagy." (PMID 34831171, 2021).
colitis (1 paper, 2023). Inflammation of the colon. "Of interest appears to be the methylation of the 3′-end region of the VMP1 gene, both in children and adults, since the VMP1 gene shares its region with the primary transcription site for microRNA-21 (pre-miR21), a microRNA implicated in the inflammatory state in colitis and IBD." (PMID 37569505, 2023).
dengue virus infection (1 paper, 2022). "Here, we dissected the role of TMEM41B and VMP1 in dengue virus infection, showing that both these proteins are crucial for the normal functionality of mitochondria and the regulation of cellular metabolites." (PMID 35939522, 2022). "We further provided evidence that these metabolic roles contribute to TMEM41B and VMP1 essentiality in dengue virus infection." (PMID 35939522, 2022).